IL6 (interleukin 6)
Diseases named in the same sentence as IL6 in open-access papers (continued):
Sharing a sentence is not in itself a finding about the gene and the disease.
tumor (continued). "Anti-IL-6 administration did not change body weight kinetics, body composition, tumor growth, serum markers of hepatocellular damage, or pre-fasting food intake." (PMID 27829137, 2016). "It has been reported previously that IL-6 induces endothelial cell proliferation, but we did not observe increased tumor angiogenesis in Chy tumors." (PMID 27329584, 2016). "In both tumor cell lines, the addition of gemcitabine to the IL-6-stimulated cells did not decrease STAT3 phosphorylation." (PMID 27687804, 2016). "Further, the Kaplan-Meier survival analysis and the log rank test revealed that neither the tumoral protein expression nor the IL-6 mRNA expressions in primary tumours or the adjacent normal tissues were able to predict DFS or OS in the PTC patients." (PMID 27034885, 2016). "This ketogenic deficit was shown to be independent of decreased fat mass and, importantly, to be induced by infusing IL-6 in the absence of a tumor." (PMID 27829137, 2016). "However, only anti‐IL‐6 produced a significant attenuation of migration of tumor cells in vitro, and enhanced tumor cells migration was seen only using EMT6 tumor cells incubated with 4THM serum, exosomes, or recombinant IL‐6." (PMID 26725371, 2016). "Lin and Karin reported that IL-10 could modulate apoptosis and suppress angiogenesis during tumor regression, downregulating VEGF, TNF-α, and IL-6 production by TAMs." (PMID 26989335, 2016). "Vice versa, MSC-derived CXCL7 stimulates the cancer cells via activation of the CXCR2 receptor and induces the synthesis of additional cytokines such as IL6 and IL8 to generate a positive feedback loop which contributes to increased MSC attraction and enhanced interactions with tumor cells." (PMID 27608835, 2016). "Treatment with Selumetinib reduced tumor mass and reduced circulating and tumor IL-6; however MEK inhibition did not preserve muscle mass." (PMID 28149280, 2016). "The circulating IL-6 levels were found to be significantly higher in male patients (P = 0.016) and in PTC patients having larger tumour size (P = 0.043), presence of metastasis (P < 0.001), and extrathyroidal extension of tumours (P = 0.019) when compared to their respective counterparts." (PMID 27034885, 2016). "Conversely, inflammatory cytokines generated by the tumour microenvironment (such as IL-6 and IL-8) with activation of NF-κB induce glycolysis with activation of PI3K and AKT and stimulate CSC self-renewal, which then may promote tumour growth and metastasis." (PMID 27220421, 2016). "In this study, it is observed that macrophage AEG-1 up-regulated the expression of IL-6, which may be responsible for STAT3 activation in tumor cells." (PMID 27793010, 2016). "In addition, several inflammatory cytokines, including TNF-α, IL-1, IL-6, TGF-β and IL-18, have been documented to increase HIF-1α expression or transcriptional activation in tumor cells." (PMID 26910835, 2016). "Of great importance, for the first time in OS, we show that elevated levels of IL-6 and TGFβ1 are provided by stromal cells, rather than tumor cells and highlight the importance of taking into careful consideration the non-tumor component of the malignancy." (PMID 27851822, 2016). "In contrast, the senescent shIL-6 MSF lines, which expressed significantly reduced levels of IL-6, failed to promote tumour cell growth compared with non-senescent MSFs expressing the same hairpins." (PMID 27272654, 2016). "Therefore, our results provide new insights into the mechanisms by which CAFs induce tumor immune escape as well as a novel cancer immunotherapeutic approach (for example, targeting CAFs, IDO or IL-6)." (PMID 26900950, 2016). "After establishing primary tumours with 9607-shIL-6 cells or control GFP-9607 cells in tumour self-seeding models, the seeding of RFP-F5M2 cells (CTCs) was significantly reduced in the IL-6 shRNA group compared with the control group." (PMID 26623559, 2016).
tumor (continued). "Moreover, embelin decreases the expression of cytokines such as IL-6, IL-1β and IL-17a, and reduces the infiltration of CD4+ T cells in the tumor stroma." (PMID 26799669, 2016). "We further studied the protein expression of IL-6 in the primary tumours of PTC patients in relation to the benign tissues and also determined its mRNA expression in the primary tumour as well as adjacent normal tissues of histologically confirmed PTC patients." (PMID 27034885, 2016). "Immunohistochemically, the carcinoma cells were faintly or focally (50 % tumor cells positive) positive for IL-6 but negative for G-CSF." (PMID 27659803, 2016). "Conversely, subsequent profiling of these macro-dissected tumor samples confirmed that PTEN status did not correlate with significant changes in intrinsic expression of other cytokines including IL-6 (Spearman correlation: −0.1091; p = 0.6378)." (PMID 26799286, 2016). "Despite the multitude of mechanisms that have been proposed to explain the hypoxia-induced autophagy of tumor cells, there are no studies evaluating the impact of prominently expressed IL6 on this cellular event." (PMID 27163161, 2016). "While a reduced tumor burden and decreased circulating levels of IL-6 were seen with Selumetinib treatment, we did not observe any protection in skeletal muscle or fat mass." (PMID 28149280, 2016). "No statistically significant main effects of tumor or interactions with time were evident for other inflammation-related genes (Il-6, Ccl5, Ccl1, Ccl22, Cx3cl1; p>0.05)." (PMID 27548621, 2016). "Immunohistochemistry was performed in order to examine IL-6 and MMP14 expression in human tumor samples and to determine whether the proteins were associated with clinical parameters such as pathological grade and patient survival." (PMID 27613828, 2016). "Since IL-6 has been suggested to promote tumor survival, CBP-induced IL-6 production might contribute to drug resistance to platinum." (PMID 27006530, 2016). "The putative mediators of tumor inhibitory effect of supernatant from the irradiated cells seem to involve radiation-induced upregulation of VEGF, PDGF, GMCSF and IL-2 and downregulation of IL-6 and SCF." (PMID 27561007, 2016). "When control shRFP-expressing MSFs were induced to senesce, they stained positive for SA-βgal, expressed increased levels of IL-6, and upon co-injection with PDSC5 tumour cells, promoted tumour cell growth 3.2-fold compared with non-senescent, shRFP-expressing MSFs." (PMID 27272654, 2016). "As our H1975 tumors were grown in athymic mice that only lack T cells, it is possible that the source of the IL-6 is from a hematological / marrow stem cell source rather than the tumor cells themselves." (PMID 26934000, 2016). "IL-6 and the activated JAK/STAT3 pathway may serve as efficient targets for blocking or suppressing tumour self-seeding." (PMID 26623559, 2016). "For instance, IL-6 expression activates signalling through Janus kinase 2 (JAK2) and Stat3, EGF increases the concentration of pre-oncogenic phosphorylated Akt, whereas CXCL12 and CCL5 stimulate tumour growth through the PI3K-Akt-mTOR pathway." (PMID 27845732, 2016). "In conclusion, these results demonstrate that short-term PDTC treatment to the cachectic mouse is sufficient to rescue cancer-induced disruptions to muscle and liver signaling, and these changes are independent of changes in tumor burden and circulating IL-6." (PMID 27449092, 2016). "Additionally, in a similar manner to that in wounds, neutrophils secrete cytokines including IL-6, IL-8, TNF-α, and GM-CSF, enhancing angiogenesis and tumor progression." (PMID 26884644, 2016). "In fact, several studies have shown that TNF-α, IL-1, IL-6 and interferon gamma (IFN-γ), released by both tumor cells and the host in response to the tumor may lead to activation of different pathways of intracellular protein degradation." (PMID 27330885, 2016).
tumor (continued). "Of note, we observed that fractionated radiation increased the secretion of IL-6 in the tumor microenvironment through the activation of the JAK/STAT3/Notch2 signaling pathway as shown in a schematic model." (PMID 27462787, 2016). "Thirdly, those pathways must also be independent of IL-6, given that circulating and tumor-derived IL-6 were reduced in our study." (PMID 28149280, 2016). "Upstream regulators predicted to modulate expression and activity of the 240 upregulated expressed murine genes in the OS-2 tumor xenografts included the T-helper cell type-17 (Th17)-activating cytokines TGF-β (P-value 1.26E–27), IL-1β (P-value 9.07E–25) and IL-6 (P-value 9.03E–22)." (PMID 27874835, 2016). "Furthermore, IL-6, IL-8 and VEGF production, as well as STAT1 phosphorylation, were increased in tumour tissues of A549-IL-17 cell-bearing nude mice in vivo and in A549 and H292 cells following IL-17 stimulation in vitro." (PMID 27819281, 2016). "Therefore, our study initially showed that hCAFs have an immunosuppressive effect upon DCs, and provided us with a novel mechanism that involves tumor immune escape and a novel cancer immunotherapeutic approach (for example, by targeting CAFs, IDO or IL-6)." (PMID 26900950, 2016). "In addition to IL-6 being deposited by the increased adipose tissue, the impaired lymphatic washout in Chy mice could potentially reduce the washout of locally produced cytokines from the tumor microenvironment, thus contributing to the increased IL-6 levels in Chy tumors." (PMID 27329584, 2016). "Further, IL-6 neutralization of senescent CM failed to impact the in vitro growth of tumour cells alone." (PMID 27272654, 2016). "Finally, IL-32 plays an important role in the tumor microenvironment by inducing the secretion of inflammatory mediators, such as TNF-α, IL-1β, IL-6, IL-8, IL-18, and MIP-2, which are related to invasion and metastasis." (PMID 27445423, 2016). "Taken together, our study indicates the autonomous MSI1-dependent regulation of AKT and IL-6 in GBM, and partly answered the unsolved question of how MSI1 takes effect on autocrine/paracrine secretion, as well as tumor environmental pro-inflammatory biogenesis." (PMID 27285760, 2016). "Furthermore, TAM-derived IL-6 induced CD44+ stemlike cell expansion by activating STAT3, and blocking IL-6 with tocilizumab ablated CD44+ sphere formation in vitro and tumor growth in patient-derived HCC xenografts." (PMID 26980947, 2016). "Tumor derived interleukin-6 increases hepatic thrombopoietin, which stimulates bone marrow megakaryocytes and platelet production of TGF-β1, which in turn activates the TGF-β1/smad proliferation pathway in tumor cells." (PMID 27502272, 2016). "We also examined the effect of IL-6 blockade on tumor cell apoptosis with or without the presence of CBP." (PMID 27006530, 2016). "The chronic host inflammatory response in cancer patients elicits muscle degradation even in the face of adequate nutrition, and cytokines including IL-6 and TNF-α produced by the host immune cells in response to a tumor are major contributors to muscle wasting." (PMID 27064118, 2016). "In addition, the number of myeloid-derived suppressor cells (MDSCs), which are induced by VEGF, GM-CSF, TGF-β, IL-6, PGE2, and cyclooxygenase (COX)-2 are often increased in tumor patients." (PMID 27044404, 2016). "The down-stream products of NF-κB: including COX-2, IL-6, IL-8, IL-1β are expressed at lower levels creating a tumour micro-environment that no longer facilitates progression or development of cancers." (PMID 27548217, 2016). "In addition to IL-6, TAF overexpression of CXCL1 (GRO-alpha) has been recently shown to induce tumor cell invasion and enhance chemotherapeutic resistance." (PMID 27515302, 2016). "Finally, intra tumor TNFα and IFNγ level was significantly reduced in DDB1F/F, Alb-Cre+/−, IL6−/− mouse comparing to DDB1F/F, Alb-Cre+/− mouse." (PMID 27556180, 2016).
tumor (continued). "It has been described that the addition of TGF-β and IL-6 during the in vitro differentiation of Th17 cells induces the expression of CD39 and CD73 ectonucleotidases by Th17 cells and that tumor-infiltrating Th17 cells may express these ectonucleotidases." (PMID 27322617, 2016). "The pro-inflammatory cytokines IL-1β, IL-6, IL-8, and VEGF promote tumor angiogenesis." (PMID 27171110, 2016). "In order to analyze the reasons for increased expression of GRO, IL6, and IL8 in human but not in PDX ascites, we considered the possibility that these cytokines were secreted by tumor‐associated stromal cells." (PMID 26833741, 2016). "IL-1β, IL-18, IL-6, IL-8 and TNF-α are produced by macrophages through the activation of toll-like receptor signaling, and their production is involved in the clearance of tumor cells by macrophages." (PMID 27671753, 2016). "Furthermore, Dubois-Pot-Schneider et al50 provide molecular evidence that TNF, IL-6 and TGF-β-related signatures are increased during dedifferentiation of tumour-derived hepatocyte-like cells to progenitor cells." (PMID 26206664, 2016). "In this study, we revealed MSI1 plays an important role in AKT activation and IL-6 secretion in response to chemo-drug in GBM cells, which eventually contributes to a dynamic interaction between proinflammatory circuits, chemoresistance, and tumor recurrence." (PMID 27285760, 2016). "It's worth noting that IL-6 was increased significantly in all TAM-S subpopulation, but decreased slightly in all TAM-M subpopulation, which indicated that the two isoforms of M-CSF in tumor microenvironment had different effects on TAMs." (PMID 26595525, 2016). "Therefore, reduced synthesis and secretion of IL-6, MCP-1, and IL-10 were, at least in part, responsible for the decreased stimulation of tumor growth and metastasis by lal−/− MSCs, which formulate a unique signature for lal−/− MSCs." (PMID 27531897, 2016). "Moreover, 14,15-EET can cooperate with G-CSF/IL-6 to more efficiently induce the enhanced and sustained activation of STAT3, thus inducing the conversion of neutrophil function from tumor-suppressing to tumor-promoting." (PMID 27270316, 2016). "IL-6 further stimulates myeloid-derived suppressor cells (MDSC) and anti-tumor T-cell activity." (PMID 27329584, 2016). "Deletion of IL6 accelerates HCC development and increases tumor burden." (PMID 27556180, 2016). "Young hosts exhibited marked tumour eradication regardless of IL-6 blockade when donor CD4+ T cells were primed with peptide-pulsed DCs, whereas as expected the antitumour effect of CD4+ T cells was impaired in control Ab-treated aged mice." (PMID 25850032, 2015). "In conclusion, patients with low baseline IL-6 and anti-SEA/E-120 may respond well to Nap by triggering T cell activation and expansion (IL-2) paving the way for anti-tumour effects documented as prolonged OS." (PMID 25669986, 2015). "However, heightened levels of IL-6 and TNF-α were observed in supernatants of human PBACs incubated with hCG-primed tumor conditioned medium." (PMID 26608647, 2015). "In fact, these are well known indicators for poor prognosis and early tumor recurrence in patients with HCC, for instance, glypican 3, MicroRNA-29, hyaluronic acid, Ski-interacting protein, interleukin-6, VEGFR2, IL-17 and IL-17RE, G2890 N-glycan, GGT and miR-24-3p." (PMID 25970775, 2015). "hCG was incapable of inducing the secretion of IL-6 or TNF-α from tumor cells (data not shown) or from PBAC." (PMID 26608647, 2015). "Inflammatory factors derive not only from the systemic reaction to malignancies, but also the secretion of tumor cells, including acute phase proteins like CRP, chemokines, cytokines like interleukin 6 (IL-6), transcription factor like NF-κB, circulating and infiltration immune cells and so on." (PMID 25934640, 2015).
tumor (continued). "Similar to our finding, a recent report in tumor immunity demonstrated that inflammatory cytokines (such as IL-6) induced by TLR stimulation were not required for the induction of anti-tumor CTL responses." (PMID 25994622, 2015). "Moreover, in aged mice treated with DC vaccination together with anti-IL-6 Ab, progression of RMA tumour was significantly repressed as observed in the MCA-OVA model." (PMID 25850032, 2015). "Leptin however upregulates pro-inflammatory and pro-tumor IL-6 yet does not alter anti-inflammatory IL-10 expression." (PMID 25599228, 2015). "In conclusion, patients with low baseline IL-6 and normal anti-SEA/E-120 may respond well to Nap by T cell activation and expansion paving the way for anti-tumour effects." (PMID 25669986, 2015). "Among genes differentially expressed between tumor samples with and without necrosis, a substantial number of hypoxia-related genes were found to be up-regulated, such as IL6, CXCL8 (IL8), SERPINE1 as well as genes involved in glycolysis (SLC2A3, LDHA)." (PMID 26485755, 2015). "Indeed, IL-6 has been demonstrated to activate STAT3/NF-κB signaling, which consequently sustains EMT in breast cancer, and to modulate the tumor microenvironment, linking inflammation to cancer progression and drug resistance." (PMID 26452030, 2015). "Myostatin and IL-6 significantly increase in the docetaxel-treated mice (TD), as opposed to that in tumor-bearing mice (T)." (PMID 25797259, 2015). "This TF induces tumour-promoting inflammation and activates pro-oncogenic pathways (in conjunction”with NF-kB and IL-6) and up-regulates many pro-inflammatory genes such as cyclooxygenase COX-2, IL-1b, IL-6, and IL-8." (PMID 25705130, 2015). "Induced by IFN-γ, IL-6, and so forth, M1 macrophages display proinflammatory, antigen-presenting, and antitumor effects, through release of soluble enzyme, TNF, and IFN and activation of T cell immune responses to inhibit tumor cells." (PMID 26161392, 2015). "Our results do not provide evidence for overexpression of apoptosis-inducing ligands by DC-tumor cell hybrids, nor did we observe an enhanced production of tolerance-inducing cytokine IL-6 or IL-10 by these cells." (PMID 26605345, 2015). "Secretion of IL-6 by J774 was significantly enhanced by treatment of W4P tumor lysates but not WT tumor lysate, and the level was lowered by estradiol, suggesting that IL-6 is produced by W4P-LHB-expressing cells and neighboring macrophages." (PMID 25645622, 2015). "Like TNF-α, IL-6 facilitates tumor development by promoting the conversion of non-cancer cells into tumor stem cells in low-attachment culture conditions by up-regulating Oct 4 gene expression through activating the IL-6R/JAK/STAT3 signaling pathway." (PMID 26418748, 2015). "To investigate whether tTF-pHLIP induces an innate immune response, we assessed IL-6, IP-10, TNF-α and IFN-α serum concentrations of non-tumor-bearing C57BL/6 mice before and after tTF-pHLIP treatment." (PMID 26143637, 2015). "Treatment with interleukin-6 did not appear to affect the antitumor activity of these agents or affect tumor growth." (PMID 25596818, 2015). "As expected, the involvement of tumor microenvironment in cancer and in its complications, such as DVT, is emphasized in the correlation between plasma levels of IL-6,TNF-α, IL-1β, VEGF and MMP-9 from cancer patients with and without DVT and those released from monocytes." (PMID 26192925, 2015). "Furthermore, direct cell-cell incubation induces an upregulation of mitotic genes Aurora B and Plk1, cytokine genes IL-6 and IL-8 and the oncogene BCL6 known for their tumor promoting functions." (PMID 26439686, 2015). "Taken together, these results suggest that elevated levels of IL-21 in the tumors of Apcmin/+ mice support a tumor-promoting inflammatory microenvironment characterized by enhanced production of IL-17A, IL-22, TNF-α and IL-6 and hyper-activation of STAT3/NF-kB." (PMID 25839161, 2015).